FBP1 (fructose-bisphosphatase 1)
Diseases named in the same sentence as FBP1 in open-access papers (continued):
Sharing a sentence is not in itself a finding about the gene and the disease.
lung carcinoma (continued). "Our data showed significantly high rate of methylation in FBP1 promoter in lung cancer tissues verses paired normal tissues, and the detected higher methylation level also corresponds to lower FBP1 expression." (PMID 29984231, 2018). "Our previous study revealed that FBP1 mRNA was significantly decreased in lung cancer tissues compared with normal tissues." (PMID 29984231, 2018). "Zinc finger E-box-binding homeobox 1 (ZEB1) bound to the FBP1 promoter to enhance DNA methylation in lung cancer." (PMID 29556139, 2018). "Moreover, targeted inhibition of FBP1 restored NK cell function in gastric cancer and lung cancer models, which opens up new avenues for NK-cell-based immunotherapy." (PMID 40100307, 2025). "Further analysis on ALDH2, ALDH3a1, FBP1, PGD, TALDO1, and TPI1 as biomarkers on the evolution of IPF patients, their association with PJ infection, and their lung cancer risk could be relevant." (PMID 39997396, 2025). "The study showed that gastric cancer mesenchymal stem cells (GCMSCs) can inhibit NK cell function by upregulating the expression of FBP1 in NK cells and decreasing glucose metabolism in NK cells; similarly in lung cancer, FBP1 impairs NK cell viability by inhibiting glycolysis in NK cells." (PMID 40100307, 2025). "For instance, FBP1 was found to be downregulated in lung cancer tissues and cells." (PMID 37737707, 2023). "Activation of FBP1 expression could inhibit glucose uptake and lactate production, induce oxygen consumption capacity, and inhibit lung cancer cell proliferation and invasion under hypoxic conditions in vitro and lung cancer growth in vivo." (PMID 37737707, 2023). "Interestingly, this opposite trend between ALDOA and FBP1 was also observed in other types of prognosis, such as lung cancer's first progression and post-progression survival." (PMID 35404841, 2022). "Similarly, low FBP1 expression was also related to improved prognosis of lung cancer first progression and post-progression survival, and vice versa, and ALDOA was correlated with poor prognosis." (PMID 35404841, 2022). "NK cell dysfunction induced by FBP1 inhibited glycolysis during lung cancer progression." (PMID 34869590, 2021). "Elevated TGF-β was also found to upregulate FBP1 in KRAS-mutant lung cancer." (PMID 33995422, 2021). "Furthermore, a recent research announced that suppression of FBP1 transcription by ZEB1 is a critical oncogenic event in lung cancer progression." (PMID 33897890, 2021). "On the other hand, FBP1 could decrease glycolytic flux in renal tubular epithelial cells and subsequently inhibits the Warburg effect in lung cancer cells as predicted." (PMID 29984231, 2018). "ZEB1 interacted with the FBP1 promoter to enhance DNA methylation in lung cancer cells." (PMID 30429463, 2018). "All these findings implied the important roles of FBP1 expression in lung cancer development and progression and the potential use of the methylation status detected in FBP1 promoter region as a novel predictor for prognosis and therapeutic target for NSCLC patients." (PMID 29984231, 2018). "In the Kras-driven lung cancer mouse model, TGF-β inhibits glycolysis in NK cells by regulating the production of FBP1, which further mediates the exhaustion of NK cells." (PMID 38022613, 2023). "Among these mechanisms, in Kras-driven lung cancer in mice, TGF-β may be involved in FBP1 upregulation in NK cells, and FBP1-mediated glycolysis inhibition and FBP1-mediated impaired viability have been confirmed to induce NK cell dysfunction." (PMID 31293580, 2019). "FBP1 was absent in lung cancer cells, and forced expression of FBP1 led to inhibition of tumorigenesis and invasion, especially under hypoxic conditions (0.1% oxygen)." (PMID 29556139, 2018). "Due to high rate CpG islands located in FBP1 gene promoter region and its possible regulation mechanisms as previously revealed, we investigated the methylation status of FBP1 promoter region in paired human lung cancer and adjacent normal tissues." (PMID 29984231, 2018).
lung carcinoma (continued). "Moreover, our study demonstrates that in lung cancer cells, the predominant form of Fbp is Fbp2, not Fbp1, and that Hif1α interacts with Fbp2 much more strongly than with Fbp1." (PMID 31947613, 2020).
gastric cancer (18 papers, 2013 to 2026). A primary or metastatic malignant neoplasm involving the stomach. "A study conducted in 2016 assessed the transcriptional levels of FBP1 and FBP2, revealing that elevated levels of FBP1 mRNA were associated with a favorable prognosis in gastric cancer." (PMID 39763587, 2024). "Studies have also revealed that reduced FBP1 expression in hepatocellular, colon, and gastric cancer is caused by DNA hypermethylation in its promoter region." (PMID 29984231, 2018). "Additionally, the inhibitory epithelial-to-mesenchymal transition (EMT) effect of FBP1 has been identified in gastric cancer, where loss of FBP1 expression supported cancer cell growth through increased glycolysis." (PMID 34436420, 2021). "FBP1 is deficiently expressed in HCC, gastric cancer, colon cancer, and nasopharyngeal carcinoma, accelerating glucose uptake and glycolysis." (PMID 40100307, 2025). "In gastric cancer, Snail inhibits the FBP1 expression at the transcriptional level to enhance glycolysis during the epithelial-mesenchymal transition." (PMID 40100307, 2025). "Subsequent verification of FBP1 protein expression confirmed that its overexpression correlated with improved clinical outcomes in patients with gastric cancer following surgical resection." (PMID 39763587, 2024). "Functional analyses further demonstrated that FBP1 expression significantly inhibited the proliferation and invasion of gastric cancer cells." (PMID 39763587, 2024). "The expression of FBP1 was downregulated in gastric cancer and gastric cancer cell lines, and this downregulation was related to the Warburg effect in tumors." (PMID 33564363, 2021). "FBP1 has been identified as having a tumor suppressive effect in prostate cancer, gastric cancer, and clear cell renal cell carcinoma (ccRCC)." (PMID 34436420, 2021). "The Rat Sarcoma (RAS)/NF-κB: nuclear factor-kappa B (NF-κB) pathway promoted DNA methylation of FBP1 in gastric cancer cells." (PMID 30429463, 2018). "This same study found that the methylation status of the FBP1 promoter alone can predict prognosis of gastric cancers, where individuals with unmethylated promoters have higher survival rates." (PMID 29922517, 2018). "NF-ΚB functioning downstream of the Ras pathway promoted the epigenetic downregulation of FBP1 in gastric cancer." (PMID 29556139, 2018). "In gastric cancer, Ras-induced FBP1 downregulation was reversed after the inhibition of NF-ΚB activity by either a chemical inhibitor of NF-ΚB, BAY11-7085, or a genetic suppressor of NF-ΚB, IkB-alpha M." (PMID 29556139, 2018). "FBP1 is a gluconeogenesis regulatory enzyme and it functions to antagonize glycolysis in gastric cancer." (PMID 24633177, 2014). "Moreover, the NF-kappaB downstream of Ras downregulates FBP1 at the transcriptional level to enhance the Warburg effect and promote gastric cancer progression." (PMID 40100307, 2025). "Lower FBP1 expression has been detected in multiple cancers, including hepatocellular, colon, gastric cancer, basal-like breast cancer (BLBC), clear cell renal cell carcinoma (ccRCC), and pancreatic cancer, and correlated with advanced tumor stages and worse patient prognosis." (PMID 29984231, 2018). "Thus, a novel biomarker for the prognosis of gastric cancer may be the promoter methylation of FBP1." (PMID 40100307, 2025). "In gastric cancer, glioma, and LUAD cells, NF-κB increases the promoter methylation of the FBP1 gene, which decreases the expression of the FBP1 protein." (PMID 40100307, 2025). "Promoter methylation of the glycolysis antagonist fructose-1,6-bisphosphatase-1 (FBP1) is promoted by the NFκB pathway, and can be used as a biomarker for prognosis prediction in gastric cancer." (PMID 34680164, 2021). "Expression of FBP1 and FBP2 was significantly downregulated in gastric cancer cell lines and gastric carcinomas (GCs) due to promoter hypermethylation." (PMID 29556139, 2018).
gastric cancer (continued). "In addition, FBP1 inhibition facilitates EMT, which increases the metastasis of gastric cancer and may be a prognostic and therapeutic target." (PMID 40100307, 2025).
cholangiocarcinoma (14 papers, 2019 to 2025). A carcinoma that arises from the intrahepatic biliary tree (intrahepatic cholangiocarcinoma) or from the junction, or adjacent to the junction, of the right and left hepatic ducts (hilar cholangiocarcinoma). "NEDD4 promotes cholangiocarcinoma progression by targeting FBP1 and inhibiting its expression through ubiquitination." (PMID 40100307, 2025). "Overexpression of FBP1 also induces the inactivation of the Wnt/β-catenin pathway to hinder cholangiocarcinoma cell proliferation, migration, invasion, and tumorigenesis." (PMID 40100307, 2025). "MT1JP attenuates the proliferation, migration, and invasion of cholangiocarcinoma cells and induces apoptosis by regulating the miR-18a-5p/FBP1 axis." (PMID 40100307, 2025). "Two NFATc2-related axes control cancer progression: the NEDD4/FBP1 axis in cholangiocarcinoma and the MYC/NFATc2 axis in acute myeloid leukemia (AML) cells." (PMID 39822413, 2024). "Another study reported that FBP1 inhibited tumorigenesis of cholangiocarcinoma partly via Wnt/β-catenin pathway." (PMID 36358906, 2022). "MT1JP alleviated proliferation, migration and invasion, and induced apoptosis in cholangiocarcinoma cells by regulating miR-18a-5p/FBP1 axis." (PMID 33557774, 2021). "In cholangiocarcinoma cells, overexpression of Fbp1 induces apoptosis and suppresses cell proliferation, migration and invasion." (PMID 33960626, 2021). "According to TCGA database, MT1JP and FBP1 were downregulated and miR-18a-5p was upregulated in clinical cholangiocarcinoma tissues." (PMID 33557774, 2021). "In our previous study, FBP1 was demonstrated to inhibit proliferation and metastasis in cholangiocarcinoma cells by regulating Wnt/β-catenin signaling pathway." (PMID 33557774, 2021). "The TCGA database shows that MT1JP is downregulated in cholangiocarcinoma specimens, and its expression is positive correlated with that of fructose-1,6-bisphosphatase 1 (FBP1)." (PMID 33557774, 2021). "FBP1 overexpression inhibits the proliferation, migration, invasion and tumorigenesis of cholangiocarcinoma cells by inhibiting the Wnt/β pathway." (PMID 33836688, 2021). "In addition, NEDD4 targets FBP1 and inhibits its expression through ubiquitination, thereby promoting cholangiocarcinoma progression." (PMID 40100307, 2025). "NFATc2 is involved in the cholangiocarcinoma progression via the NEDD4/FBP1 axis." (PMID 39822413, 2024). "Because MT1JP has previously been reported to act as a miRNA sponge, we hypothesized that MT1JP functioned by sponging miR-18a-5p and regulating FBP1 expression in cholangiocarcinoma." (PMID 33557774, 2021). "Similarly, FBP1 was proven to inhibit tumor progression in cholangiocarcinoma (CCA), prostate cancer (PCA), and lung adenocarcinoma (LUAD)." (PMID 35127693, 2021). "For example, overexpression of Fbp1 in cholangiocarcinoma enhances apoptosis." (PMID 33960626, 2021). "In addition, GEPIA website showed that the expression level of MT1JP was positively correlated with that of FBP1 in cholangiocarcinoma tissues." (PMID 33557774, 2021). "FBP1 was found to restrain malignancies in cholangiocarcinoma cell in our previous study." (PMID 33557774, 2021). "Additionally, lncRNA DANCR upregulates FBP1 to accelerate proliferation and migration in cholangiocarcinoma via interacting with EZH2." (PMID 33292221, 2020). "In addition, FBP1 was found to inhibit the Wnt/β‐catenin pathway in cholangiocarcinoma cells." (PMID 34854226, 2022). "In cholangiocarcinoma (CCA) cells, DANCR binds to EZH2 to facilitate histone methylation of the FBP1 promoter, ultimately suppressing FBP1 expression via epigenetic mechanisms." (PMID 38877534, 2024). "In cholangiocarcinoma, DANCR-EZH2 interaction promoted FBP1 silence by regulating histone methylation of FBP1 promoter and then exacerbating tumorigenesis." (PMID 34722539, 2021).
Hypoglycemia (14 papers, 2018 to 2025). A decreased concentration of glucose in the blood. "Fructose-1,6-bisphosphatase (FBP1) deficiency is a rare inherited disease characterized by recurrent episodes of lactic acidosis and ketotic hypoglycemia." (PMID 41327277, 2025). "The majority of patients in the present study exhibited the classic biochemical hallmarks for FBP1 deficiency, including hypoglycemia, hyperlactatemia, metabolic acidosis, and ketonuria." (PMID 41327277, 2025). "The clinical hallmark of FBP1 deficiency is recurrent episodes of lactic acidosis and ketotic hypoglycemia during early childhood." (PMID 41327277, 2025). "An autosomal recessive inherited disorder of FBP1 deficiency is characterized by hypoglycemia and lactic acidosis, which often results in sudden infant death." (PMID 38834617, 2024). "Clinical suspicion for FBP1 deficiency should be heightened in cases presenting with acute infection onset, severe metabolic acidosis, and hypoglycemia." (PMID 39301409, 2024). "FBP1 deficiency is a spectrum disorder that should be considered in children presenting with symptoms such as failure to thrive, recurrent hypoglycemia, and/or metabolic acidosis." (PMID 39301409, 2024). "The family members with a homozygous FBP1 variant presented with lactic acidosis and hypoglycemia, a sign of reduced FBP1 function." (PMID 37388727, 2023). "Massively parallel sequencing of genes associated with hypoglycaemia identified a previously reported homozygous likely pathogenic variant (c.705 + 5G>A) in FBP1, confirming a diagnosis of fructose-1,6-bisphosphatase deficiency." (PMID 36561316, 2022). "In fructose-1,6-bisphosphate deficiency of the liver enzyme FBP1, acute attacks with hypoglycemia and lactic acidosis are often triggered by febrile infections." (PMID 33977262, 2021). "Pathogenic FBP1 gene mutations impair FBPase activity, causing patients unable to effectively metabolize pyruvate and lactate to glucose for energy demand during fasting or infection, leading to hypoglycemia and metabolic acidosis." (PMID 39036704, 2024). "Although Fbp1 homozygous (Fbp1−/−) newborn mice were morphologically indistinguishable from WT littermates (Fbp1+/+), they died several days after birth, which might be caused by hypoglycemia and lactic acidosis observed in FBP1 deficient human infants." (PMID 38834617, 2024). "PCK1, PCK2, and FBP1, when deficient, have all been associated with hypoglycemia, and may have been upregulated as a compensatory mechanism to potentially provide needed intermediates within the glycolytic pathway." (PMID 38731997, 2024). "Loss of FBP1 could cause lactic acidosis and hypoglycemia and even unexpected death to infants." (PMID 39902328, 2025). "The homozygous FBP1 deletion was also found in sister IX, whose main clinical manifestations were episodes of hypoglycemia and increased lactate, ranging from 2.7-7.8 mmol/L." (PMID 37388727, 2023). "FBP1 plays a central role in gluconeogenesis, which becomes obvious in a rare inherited disorder, namely fructose-1,6-bisphosphatase deficiency (OMIM database entry #229700) where the patients suffer from severe hypoglycemia and metabolic acidosis on fasting." (PMID 36613872, 2022). "Nevertheless, deletion of Bicc1 in mice led to hypoglycemia and diminished the expression of FBP1 and PEPCK specifically in kidneys but not in liver, correlating with increased accumulation of CTLH complex." (PMID 29995892, 2018).
liver cancer (14 papers, 2011 to 2024). An epithelial or non-epithelial malignant neoplasm that arises from the liver. "Recent work suggested that FBP1 is a metabolic tumor suppressor in liver cancer and that loss of FBP1 disrupts liver metabolic homeostasis and promotes tumor progression." (PMID 35672803, 2022). "The group with DUOX1, GLS2 and FBP1 low expression may have 2.562, 2.540 and 3.529 times risk of liver cancer relapse compared with these genes high expression group." (PMID 27079415, 2016). "Recently, it has been demonstrated that the TRIM28-MAGE complex degrades FBP1 in liver cancer cells." (PMID 34440587, 2021). "Methylation of FBP1 promoter was readily detected in liver cancer cell lines HepG2, HuH7, HCC-LM3, BEL-7402, SMMC-7721, Sk-Hep1, MHCC-97H and MHCC-97L, and human colon cancer cell lines HT29, SW480, SW620, HCT116, LoVo and RKO." (PMID 22039417, 2011). "The effect of exogenous FBP1 expression on the growth of human liver cancer cells was investigated by a monolayer colony formation assay." (PMID 22039417, 2011). "The expression of FBP1 was dramatically downregulated in 66.7% (6/9) human liver cancer cell lines including HepG2, BEL-7402, SMMC-7721, Sk-Hep1, MHCC-97H and MHCC-97L when compared to human normal liver cells Lo2." (PMID 22039417, 2011). "Similarly, the expression of fructose 1,6-bisphosphatase 1 (FBP1) is lost in both human and murine liver cancer." (PMID 37108625, 2023). "Specifically, promoter-rich methylated cytosine residues, non-acetylated histone 3 lysine 27 in enhancer regions, and chromatin interaction of the histone methyltransferase, EZH2, have all been identified as mechanisms of epigenetic repression for FBP1 in liver cancer." (PMID 35123542, 2022). "In the liver cancer, LIX1L interacts with miR-21-3p, upregulating its expression, which in turn targets and suppresses FBP1 expression, ultimately enhancing glucose consumption and lactic acid production." (PMID 38911375, 2024). "The mRNA expression of GCGR, G6PC, FBP1, and PCK1 are decreased in patient tumors and heavily silenced in many established liver cancer cell lines." (PMID 35123542, 2022). "The results showed that UBE2C, PTTG1, TOP2A and SPP1 were positive, FCN3, SLC22A1, ADH4, CYP2C8, SLC10A1, and FBP1 were negative in liver cancer tissues." (PMID 38664521, 2024). "Moreover, FBP1 is post-transcriptionally modulated by the MAGE-tripartite motif-containing 28 (TRIM28) complex and USP44 in PDAC and liver cancers." (PMID 34440587, 2021). "What’s more, the scoring system including DUOX1, GLS2 and FBP1 acted as predictive model firstly used in our study to predict HCC patients’ survival and this predictive model can be a potential prognostic tool for liver cancer patients." (PMID 27079415, 2016). "Low FBP1 expression was significantly correlated with alpha-fetoprotein (AFP) ≥ 20 ng/ml (P = 0.026), portal vein tumour thrombus (PVTT) (P = 0.020), satellite nodule (P = 0.006), advanced TNM stage (P = 0.001) and advanced Barcelona Clinic Liver Cancer stage (BCLC stage; P = 0.001)." (PMID 30429463, 2018).